IGLV4-60 (immunoglobulin lambda variable 4-60)
Description:
V region of the variable domain of immunoglobulin light chains that participates in the antigen recognition. Immunoglobulins, also known as antibodies, are membrane-bound or secreted glycoproteins produced by B lymphocytes. In the recognition phase of humoral immunity, the membrane-bound immunoglobulins serve as receptors which, upon binding of a specific antigen, trigger the clonal expansion and differentiation of B lymphocytes into immunoglobulins-secreting plasma cells. Secreted immunoglobulins mediate the effector phase of humoral immunity, which results in the elimination of bound antigens. The antigen binding site is formed by the variable domain of one heavy chain, together with that of its associated light chain. Thus, each immunoglobulin has two antigen binding sites with remarkable affinity for a particular antigen. The variable domains are assembled by a process called V-(D)-J rearrangement and can then be subjected to somatic hypermutations which, after exposure to antigen and selection, allow affinity maturation for a particular antigen.
Synonyms: IGLV460; V5-4
Gene: Immunoglobulin variable (V) gene on chromosome 22 (22,162,199 to 22,162,681, forward strand). Ensembl gene ENSG00000211639.
Subcellular location: Secreted; Cell membrane
Gene Ontology:
Biological process: immune response
Cellular component: extracellular region; immunoglobulin complex; plasma membrane
Homologues: Paralogues in human: IGLV4-69 (80% identical), IGLV5-52 (62% identical), IGLV5-37 (60% identical), IGLV9-49 (60% identical), IGLV4-3 (58% identical), IGLV5-45 (58% identical), IGLV1-40 (52% identical), IGLV1-50 (52% identical), IGLV2-18 (52% identical), IGLV1-44 (51% identical), IGLV11-55 (51% identical), IGLV2-11 (50% identical), and 81 more.